IL5 (interleukin 5)
Diseases named in the same sentence as IL5 in open-access papers (continued):
Sharing a sentence is not in itself a finding about the gene and the disease.
parasitic infections (40 papers, 2006 to 2025). "Susceptibility to parasite infection is a theoretical concern with anti-IL5 and anti-IL-4Rα therapy owing to the central role of type 2 immunity in parasite host defense." (PMID 37265457, 2023). "Because of IL-5’s association with parasitic infections, we examined the presence of parasites in each group and found parasitic coinfections in 30.7% of the children examined, many of whom did not have diarrhea (data not shown)." (PMID 35924851, 2022). "IL-5 has been described as a Th2-cell cytokine whose expression is upregulated in inflammatory-associated conditions associated with parasitic infections, similar to IL-4 or IL-13, with secretion of IL-5 by astrocytes and microglia having been described." (PMID 26834537, 2015). "In fact, Il5−/− mice exhibit less hepatic fibrosis following parasite infection, while IL-13 appears to drive an alternative TGF-β–independent pro-fibrotic pathway in MASH." (PMID 41275524, 2025). "Similar to Th2 cells, ILC2s are elicited during parasitic infections and regulate tissue immunity and inflammation by producing Th2 cytokines (IL-4, IL-5- and IL-13) to recruit and activate eosinophils and alternatively activated macrophages." (PMID 39250522, 2024). "In all four experiments where parasites reduced severity of EAE, treatment with an anti-IL-5 mAb commencing at 10 days after immunization significantly reduced the beneficial effect of parasitic infection." (PMID 29163523, 2017). "Given that blocking IL-5 eliminated the effects of parasitic infection on EAE, we examined if treatment with rIL-5 alone modified the course of EAE." (PMID 29163523, 2017). "Our interpretation of the effects of parasitic infection is that production of IL-4 and IL-5 by the activated Th2 cells and ILC2 accelerates the induction of autoantigen-specific Treg that express Il5ra, which in turn, reduced the severity of EAE." (PMID 29163523, 2017). "During parasitic infections, the increase in the number of peripheral blood is driven by Th2-derived cytokines, i.e., IL-5, IL-3." (PMID 28620263, 2017). "To test Koch’s postulate, we showed treatment with IL-5 reduced the severity of EAE to a degree comparable to parasite infection." (PMID 29163523, 2017). "These parasite-infected hosts were treated with a monoclonal antibody (mAb) that inhibits IL-5 at the time of peak IL-5 production, which blocked the beneficial effects of parasite infections and reduced induction of antigen-specific Treg." (PMID 29163523, 2017). "In three experiments, anti-IL-5 mAb treatment reversed the delay in onset of EAE seen with parasite infection, and the severity of EAE was similar to or more severe than non-infected controls." (PMID 29163523, 2017). "This was consistent with the parasite infection via induction of IL-5 production, accelerating induction of antigen-specific CD4+CD25+ T cells." (PMID 29163523, 2017). "We also showed IL-5 treatment, as with parasitic infection, increased the number of CD4+CD25+ Treg that expressed Il5ra." (PMID 29163523, 2017). "The results of this study suggested that IL-5 produced by the type-2 inflammatory response to parasite infection promoted induction of autoantigen-specific CD25+Il5ra+ T regulatory cells that reduced the severity of autoimmunity." (PMID 29163523, 2017). "With parasitic infection and rIL-5 therapy, these autoantigen and IL-4 activated Treg were further expanded, respectively, by parasite infection-induced host type-2 response producing IL-5 or by administered IL-5." (PMID 29163523, 2017). "Parasitemia was significantly correlated with the following cytokines, in order of strength of association: IL-10, IL-12, TNF-α, IFN-γ, IL-1β, IL-6, IL-5, IL-2, IL-4, and IL-7." (PMID 27418744, 2016). "IL-5 is also upregulated not only in inflammatory conditions with parasitic infections but also in neurodegenerative disorders, including Parkinson’s disease." (PMID 27402089, 2016).
parasitic infections (continued). "For instance, γδ T cells showed a Th1 effect by generating IL-2 and INF-γ when bacterial infection occurred inside cells; but showed a Th2 effect by stimulating B cells with IL-4 and IL-5 with extracellular parasite infection." (PMID 24460842, 2014). "The results from many studies have clearly identified IL-4/IL-5/IL-10 as important regulatory cytokines in parasitic infections, such as infection by Schistosoma mansoni in mice and humans, Schistosoma haematobium, Trichuris muris, and Trichinella spiralis." (PMID 24637903, 2014). "The TH2 phenotype is featured in responses to parasitic infections and is prominent in allergic responses, with IL-4, IL-5, and IL-13 as abundant cytokines." (PMID 16396683, 2006). "When it comes to innate immunity, IL-33 potently stimulates innate lymphoid cells type 2 (ILC2s), facilitating their proliferation and secretion of type 3 cytokines such as IL-5 and IL-13, which are essential in responses to parasitic infections and allergic inflammation." (PMID 41284319, 2025). "Recently, it was reported IL-5 and IL-33 may mediate the protective effect of parasite infection on autoimmunity." (PMID 29163523, 2017). "We hypothesize that, in parasite infections, IL-5 also promotes expansion of antigen-specific T regulatory cells that control autoimmunity." (PMID 29163523, 2017). "IL-4 produced early in the response to parasitic infection may have contributed to the initial activation of antigen-activated Treg to induce expression of il5ra and subsequent dependence on IL-5." (PMID 29163523, 2017). "It was confirmed that cytokines such as IL-12, TNF-α, IFN-γ, and IL-2 play an important role in controlling the proliferation of Babesia in the early and acute stages of infection, while IL-10, IL-4, IL-5, and IL-6 may involve in chronic and low parasitemia stages of infections." (PMID 32733477, 2020). "In the present study, the correlation between the Th2-type cytokine IL-5 and the Th1-type cytokines IFN-γ and IL-1β in AE patients may be associated with the enhanced immunological response induced by parasite infection, which indicates that an inflammatory reaction is induced in AE patients." (PMID 32539714, 2020). "This confirmed that the effects of parasite infection could have been mediated by IL-5 alone." (PMID 29163523, 2017). "In humans, none of the anti-IL5 monoclonal antibodies have shown a signal of increased parasite infection in clinical trials or real-world data, even in areas where parasitic infection is endemic." (PMID 37265457, 2023). "The beneficial effect of parasitic infection was abolished with an anti-IL-5 or an anti-CD25 monoclonal antibody (mAb), but not anti-IL-4 mAb." (PMID 29163523, 2017). "The significant induction of IL-4 and IL-5 in the current study might reflect unknown cytokine functions in ECM development, which might be highlighted by nahG+ parasite infection." (PMID 26466097, 2015). "The source of the IL-5 in our hosts was not identified but could be Th2 or ILC2 cells that have been activated in response to parasitic infection." (PMID 29163523, 2017). "The effects of parasite infection on EAE in IL-5 knock out animals are not known." (PMID 29163523, 2017). "Moreover, anti-IL-5 or anti-CD25, but not anti-IL-4, can abolish the beneficial effect of the parasitic infection." (PMID 35625566, 2022). "Whether or not the benefits of chronic parasitic infection where numbers of CD4+CD25+ T cells are increased in patients with MS is mediated in part or mainly by IL-5 requires investigation." (PMID 29163523, 2017).
viral infection (40 papers, 2008 to 2025). "However, these cells did express a higher amount of the T helper type 2 (TH2) cell–associated cytokines IL-5 and IL-13 at day 10 of viral infection in L. paracasei-administrated mice." (PMID 28931041, 2017). "The next step was performing a classical ELISA for representative cytokines important for viral infection—IL-4, IL-5, IL-6, IL-10, IL-17, and TNF alpha." (PMID 40358160, 2025). "TSLP is released from the airway epithelium in response to allergens, viral infection, and type 2 cytokines, and it activates dendritic cells and ILC2s to promote Th2 inflammation, positioning it upstream of the IgE, IL-5, and IL-13 pathways." (PMID 41487819, 2025). "Although none of the cured Mpox individuals enrolled in our cohort had severe symptoms, we reported significant modulation of IL-5, indicating the development of a Th2 memory response to fight the virus infection." (PMID 39339995, 2024). "It was noteworthy that the asthmatics with respiratory viral infections showed delayed but lasting Th2 airway response, as evidenced by accumulated upregulation of IL-4 and IL-5 levels until day 14 upon viral infections." (PMID 37865742, 2023). "Eosinophils play an important role in protecting the host against viral infections, and several publications discuss the eosinophils/IL-5 axis in the COVID-19 illness." (PMID 36431118, 2022). "CD4+ T cells are activated via the secretion of Th2-related cytokines (IL-4, IL-5) to stimulate B cells for the production of antibodies to prevent viral infection." (PMID 35632667, 2022). "IL-5 is also known for their stimulatory potential to B cells for humoral immune response and its role in promoting immunopathology during viral infections." (PMID 31008105, 2019). "In asthmatics IFN-γ, CXCL10/IP10, CXCL11/ITAC, IL-15 and IL-5 increased in bronchial lining fluid following viral infection (all P < 0.05)." (PMID 28373098, 2017). "Here L. paracasei–fed mice showed an expansion of TH2 cells after viral infection, which suggest that IL-13 and IL-5 produced by T cells have beneficial effects for the tissue homeostasis." (PMID 28931041, 2017). "Nevertheless, it has been reported that viral infection in an allergic environment can induce IL-5 synthesis by CD8+ T cells, probably due to PRR activation in DC." (PMID 29137638, 2017). "We found that proinflammatory cytokine (IL-5, IL-4, and IL-6) production was significantly increased later in the P17 (MA) viral infection process (at 5 dpi) compared with the parent (P0) virus infection." (PMID 26526113, 2015). "Cytokines and chemokines that showed limited response in mice with any viral infection included Eotaxin, GM-CSF, IL-1α, M-CSF, IL-2, IL-3, IL-4, IL-5, IL-7, IL-9, IL-12p40, IL-13, IL-15, IL-17, MIP2, LIX, MIP1β, RANTES, IL-12p70, and VEGF (data not shown)." (PMID 23441208, 2013). "IL-5 also influences eosinophils that can play a protective role by helping clear viral infection." (PMID 40910046, 2025). "In an animal study, after viral infection in 25(OH)D3-fed mice, the proinflammatory cytokines interleukin-5 (IL-5) and Interferon gamma (IFN-γ) were significantly downregulated, indicating that 25(OH)D3 decreases the production of inflammatory cytokines and viral replication." (PMID 35334804, 2022). "IL-5 is a key component of the immune system’s defense against a variety of viral infections." (PMID 36405584, 2022). "The pharmacological blockade of type 2 inflammation by therapeutic antibodies against IgE, IL-5, or IL-5/IL-4/-13 receptors, so far has not been suspected to increase the risk of viral infections, also in the respective approving clinical trials." (PMID 33767626, 2021). "The blocking of type 2 inflammation by therapeutic antibodies against IgE, IL-5, or the IL-5 or IL-4/-13 receptors has so far not been suspected to increase the risk of viral infections." (PMID 32915172, 2020). "However, the influence of IL-5 inhibition on mast cell responses to virus infection remains unclear." (PMID 35313976, 2022).
viral infection (continued). "Higher levels of inflammatory mediators like IL-25, IL-1β, IL-10, IL-5 and tumor necrosis factor (TNF) -α after viral infection were found in human nasal epithelial cell (HNEC) culture compared to controls." (PMID 38116043, 2023). "To further investigate the Th1/Th2 balance in airways of asthmatics during viral infection, we analyzed the ratios of IFN-γ/IL-4 and IFN-γ/IL-5 cytokines." (PMID 37865742, 2023). "IL-6 was measured in models of virus infection (influenza A/H1N1, H1N1) and bacterial infection (lipopolysaccharide, LPS), while IL-5 was measured in an allergen exposure (house dust mite, HDM) model in cell culture supernatants." (PMID 37432355, 2023). "In the course of viral infection, Th2 CD4+ T cells promote the humoral immune response by secreting IL-4, IL-5, IL-10 and other Th2 cytokines." (PMID 35100303, 2022). "After pdmH1N1 virus infection, cigarette smoke exposed mice had significantly higher production of IL-1α, IL-1β, IL-2, IFN-γ, KC, RANTES on day 3; IL-5, IL-10 and MIP-1α both on day 1 and day 3 in the lungs than the control mice." (PMID 24465940, 2014). "Down-regulation of IL15, NOS2A, CCR4 and up-regulation of IL17, CYP7A1, SELE, IL5, RPL3L genes in both patient categories indicative of response to p-H1N1-09 virus infection." (PMID 20957032, 2010). "In the case of viral infections, elevated levels of various inflammatory cytokines, including IL-1β, IL-6, IL-7, IL-17, IFN-γ, IL-8, TNFα, and GM-CSF are observed, alongside IL-4 and IL-5." (PMID 37692890, 2023). "The leading contribution of MCs in response to viral infection might be in the context of the producing panel of mediators (amines, tryptase, chymase) and cytokines/chemokines (TNF-α, IL-4, IL-5, IL-6, IL-13, and IL-17)." (PMID 32185237, 2020). "Additionally, the proinflammatory cytokines IL-5 and IFN-γ were significantly downregulated after viral infection in 25(OH)D3-fed mice, while anti-inflammatory cytokines were not significantly upregulated." (PMID 32635656, 2020). "In V + V+, the lack of increase in IL-5 levels suggests that virus-infections don’t directly influence IL-5 in this subgroup." (PMID 29137638, 2017). "Viral infection of mice normally increases interferon but not IL-5, whereas viral infection of sensitized mice increases IL-5 but not interferon." (PMID 18335107, 2008). "However, it has been shown that CD4+ T cell expression of Th2-type cytokines including IL-4 and IL-5 does not promote recovery from viral infection, but rather increases lung viral burdens." (PMID 25500584, 2014). "The levels of the anti-inflammatory cytokine IL-10 and of the proinflammatory cytokines IL-5, TNF-α, IFN-γ, and GM-CSF increased after viral infection in both groups, regardless of 25(OH)D3 intake." (PMID 32635656, 2020). "Although the TGFβ2 factor, recently recognized as a key factor in fibrosis induction, did not result upregulated by virus infection in HUVECs, other factors belonging to TGFβ superfamily were promoted in particular by HHV-6A, including GREM1 and INHBE, IL-4, IL-5, TNF, and MMP9." (PMID 31878218, 2019). "Meanwhile, the levels of IL-5 and IL-13, which are Th2 cytokines, were significantly higher in the BALF of OVA mice than those of PBS mice before infection (Day 0) although they declined after infection (Day 3) regardless of virus infection." (PMID 28245238, 2017).
chronic rhinosinusitis (39 papers, 2006 to 2026). Chronic form of sinusitis. "The pathogenesis of chronic sinusitis is still unclear; however, the nasal cavity and paranasal sinuses are commonly affected by type 2 inflammation, which is caused by Th2 cytokines such as interleukin (IL)-5, IL-4, and IL-13." (PMID 36983684, 2023). "Moreover, high levels of CLCs, chemokine (C-C motif) ligand 17, cystatin SN, interleukin (IL)-5, and macrophage inflammatory protein-1β in nasal secretions have been found to be associated with poor prognosis in chronic rhinosinusitis patients under surgical and conventional medical treatments." (PMID 36838965, 2023). "Chronic rhinosinusitis with nasal polyps (CRSwNP) is a subtype of chronic rhinosinusitis characterized by persistent eosinophilic inflammation and activation of the type 2 immune pathway, particularly involving interleukins IL-4, IL-5, and IL-13." (PMID 41281095, 2025). "It has been demonstrated that IL-5 gene expression is increased in ILC2s and that IL-5 protein levels are elevated after stimulation with S. aureus lysate in nasal tissue of patients with chronic rhinosinusitis." (PMID 39148911, 2024). "It has been proved that Th2 cells bound to IL-4, IL-5 and IL-13 play the main role in the form of chronic sinusitis with polyps." (PMID 34198970, 2021). "Anti-IL-5 and anti-IL-4 receptor α treatments have had promising effects in treating patients suffering from chronic rhinosinusitis with nasal polyps and eosinophilic asthma." (PMID 31134050, 2019). "Disrupting this loop with anti-IL-5 antibodies was beneficial for treating chronic rhino-sinusitis in humans." (PMID 31134050, 2019). "Moreover, studies on chronic sinusitis suggested the presence of specific clusters of patients showing an IL-5 driven phenotype with a peculiar expression of other cytokines (e.g., TNFα) underlining the need of better characterizing these patients from a molecular point of view." (PMID 34356836, 2021). "In parallel, cluster analysis performed on a European cohort of patients suffering from chronic rhinosinusitis demonstrated that 2 main endotypes could be distinguished: an IL‐5‐high (eosinophilic) endotype linked to type 2 immunity and an IL‐5‐low (noneosinophilic)‐driven disease." (PMID 34617355, 2021).